IRF4 (interferon regulatory factor 4)
Diseases named in the same sentence as IRF4 in open-access papers (continued):
Sharing a sentence is not in itself a finding about the gene and the disease.
tumor (continued). "Following DT treatment, a decline in tumor control correlated with the depletion of PD-1+IRF4.GFP+, Tim-3+IRF4.GFP+, and TIGIT+IRF4.GFP+ CD8+ TILs, indicating that these markers denote activated and functional TILs in this context." (PMID 38178902, 2023). "Collectively, BTK inhibition by tirabrutinib led to the suppression of NF-κB and ERK signaling, followed by downregulation of IRF4- and MYC-targeted genes, resulting in anti-tumor activity in TMD8." (PMID 36897912, 2023). "High levels of IRF4 in CD8+ T cells contribute to the clonal expansion of SLECs, which are critical for maintaining effective anti-tumor immunity and acute pathogen control." (PMID 36814912, 2023). "Lastly, we performed a temporal deletion of the Irf4 gene in antitumor CD8+ T cells during ACT, starting from 20 days after tumor implantation, which significantly compromised tumor control." (PMID 38178902, 2023). "Firstly, depleting IRF4.GFP+ CD8+ TILs derived from ACT significantly accelerated tumor growth, emphasizing their crucial role in controlling tumor progression." (PMID 38178902, 2023). "IRF4 is essential for the sustained differentiation and proliferation of CD8+ cytotoxic T cells (CTLs) and T helper 1 (Th1) cells, promoting anti-tumor immunity." (PMID 36814912, 2023). "In our study that employed the Irf4–/–TCF1GFP Pmel-1 ACT model, we observed that IRF4 deletion significantly reduced the frequency of transferred Pmel-1 cells in tumor-bearing mice." (PMID 38178902, 2023). "And lastly, CD8+ T cells in the tumor periphery exhibited a transcription factor profile of exhausted T cells with high expression of NR4A1, MAF, and IRF4, which were implicated in T cell dysfunction and exhaustion." (PMID 38127790, 2023). "We also found that IRF1, IRF3, IRF4, IRF5 and IRF7 were significantly higher in tumor stage III/IV or grade 3/4 compared with tumor stage I/II or grade 1/2, whereas the expression level of IRF6 was lower in tumor stage III/IV or grade 3/4." (PMID 37182129, 2023). "By administering diphtheria toxin to tumor-bearing Irf4GFP-DTR mice, we partially depleted IRF4.GFP+ TILs and observed an accelerated tumor growth." (PMID 38178902, 2023). "Interferon regulatory factor 4 (IRF4) can enhance the inhibitory potential of Tregs and promote tumor growth in vivo." (PMID 35740562, 2022). "CD40 engagement on HRS cells increased both tumor growth and survival, upregulated CD54, CD80, and IRF4 expression, augmented the secretion of IL-8, TNF-α, IL-6, LT-α and CCL5, decreased Fas-mediated apoptosis and increased NF-kB activation." (PMID 35626032, 2022). "MiR-125b, by targeting interferon regulatory factor 4 (IRF4), potentiates the functional role of macrophages in inducing immune responses and anti-tumor activities." (PMID 36142450, 2022). "Tumor cells express high levels of CD30, CD40, IRF4, CD15 and constitutively active nuclear factor kappa B (NF-κB)." (PMID 35626032, 2022). "Immunophenotypically, tumor cells express B-cell markers (CD20, CD79a, PAX5) with a strong expression of IRF4/MUM1 and BCL6." (PMID 34283060, 2021). "Inhibition of IRF4 enhances the expression of BCL6, thereby stabilizing the level of Tregs and suppressing the anti-tumor immune response." (PMID 33468159, 2021). "This combination led to complete tumor growth arrest, accompanied by a significant reduction in MYC, IRF4 (interferon regulatory factor 4) and Ikaros positive cells by immunohistochemistry." (PMID 35582389, 2021). "In the tumor invasion experiment, B16 tumor cells were co-cultured with PMN-MDSCs derived from the spleens of both WT and IRF4 KO mice for 18 h." (PMID 33708218, 2021). "The results showed that 5 proteins (ADAM23, ARHGAP20, ICOS, IRF4,MMRN1) were significantly different in tumour tissues compared with normal tissues." (PMID 33949771, 2021).
tumor (continued). "Increased in vivo efficacy by A2AR-knockdown CAR T cells was associated with increased expression of effector-related genes in tumor-infiltrating CD8+NGFR+ CAR T cells such as IFNγ, TNF, IRF4, and Granzyme B." (PMID 34050151, 2021). "Myeloid (LysM)-specific depletion of IRF4 led to increased tumor weight and a moderate splenic M-MDSC expansion in tumor-bearing mice." (PMID 32448983, 2020). "Lenalidomide is an immunomodulatory agent that downregulates IRF4/MUM1 and subsequently decreases BCR-dependent NF-κB activity in ABC-DLBCL cells in vitro and in tumor xenograft models." (PMID 31097684, 2019). "There was only one tumor suppressor (CSF2) and one cancer census gene in Cluster 3 (USP6); there are four tumor suppressors (GALR1, IRF4, PTPRT and SOX11) and one more cancer census gene in Cluster 4 (NRG1)." (PMID 28198667, 2017). "In mice, addition of CPI203 to lenalidomide therapy further decreased tumor burden, involving simultaneous MYC and IRF4 down-regulation and apoptosis induction." (PMID 25849938, 2015). "IRF4 is an oncoprotein with anti-apoptotic properties and IRF8 functions as a regulator of apoptosis and tumor suppressor in many hematopoietic malignancies." (PMID 23658517, 2013). "We show that IRF4 is stabilized by EBNA3C, which resulted in downregulation of IRF8 through proteasome-mediated degradation and subsequent inhibition of its tumor suppressive activity." (PMID 23658517, 2013). "To evaluate the predictive power of HERC2 and IRF4 genotypes, we built a genetic classifier of chromosome 3 status and applied this classifier to predict outcomes in patients for whom tumor status was not available." (PMID 41377059, 2026). "Our results suggested that IRF4 promotes BCL6 and thereby may contribute to tumor progression in ccRCC." (PMID 40607252, 2025). "Another hypothesis is that thiostrepton affects other transcription factor networks critical to Treg identity and function, such as IRF4, BATF, and Helios, which together orchestrate the effector Treg program within the tumor microenvironment." (PMID 40820379, 2025). "Persistent IRF4 expression may thus contribute to TLS immaturity, limiting effective anti-tumor immune responses in the ccRCC microenvironment." (PMID 40607252, 2025). "CRISPR screens have discovered that TOX can promote CD8 + T cell exhaustion in collaboration with NR4A, and TOX serves as a significant downstream regulatory molecule reversing tumour-infiltrating T cell exhaustion with BATF and IRF4, which were the hits in several CRISPR screenings." (PMID 38581063, 2024). "Manipulating IRF4 may be an important therapeutic target for reversing T cell exhaustion and TME disorders, thus promoting anti-tumor immunity." (PMID 38773508, 2024). "In addition, the inhibition of IRF4, IRF5, IRF7, and IRF8 decreases the survival of PC patients, indicating these IRFs probably act as anti-tumor factors in PC." (PMID 39384770, 2024). "These evidences illustrate that IRF1, IRF4, IRF5, IRF6, and IRF8 may be candidate tumor-suppressors in CRC." (PMID 39384770, 2024). "Macrophages could be polarized to the tumor growth-promoting M2 subtype in the tumor environment by cytokines, such as CCL2, CCL5, CCL18, and TGFB1 and the mRNA levels of the transcription factor IRF4." (PMID 39272860, 2024). "Additionally, a differential expression of the cytokine genes CCL2, CCL20, TGFB1, and TGFB2; the transcription factor gene IRF4; and the receptor genes CCR2, IL10RB, TGFBR1, and TGFBR2 was identified in tumor tissue and vestibular nerve tissue." (PMID 39272860, 2024). "TCF1GFP Pmel-1 ACT significantly inhibited B16F10 tumor growth, while tumor growth in the Irf4–/–TCF1GFP Pmel-1 ACT group was comparable to the No ACT group." (PMID 38178902, 2023). "Notably, the differences between tumor and normal cells in NUCB1 mRNA expression were more pronounced than for IRF4 and ANXA5." (PMID 36611989, 2023).
tumor (continued). "While most of the patients received chemotherapy with or without radiation, eight IRF4+ patients received mere surgical resection of the tumor and exhibited excellent outcome." (PMID 37081786, 2023). "Immunofluorescent staining revealed a marked decrease in cell numbers and IRF4 expression in inoculated tumours from the combined treatment group but not in those from other groups." (PMID 37581569, 2023). "Lack of IRF4 in murine CLL contributes to tumor immune evasion by reducing the numbers of antigen-experienced, potentially tumor-specific T cells and is associated with a more aggressive disease." (PMID 36495369, 2023). "Overall, reduced level of IRF4 seems to improve CLL homing to lymph nodal compartment, BCR activation and tumor immune evasion, but it may also potentially contribute to differentiation arrest." (PMID 36495369, 2023). "We stained the tumor-infiltrating CAR T cells for TCF1, TBET, EOMES, GATA3, ID2, ID3 and IRF4." (PMID 37945901, 2023). "Here, the authors utilise single cell RNA-seq to show the abundance of double-negative T cells in IRF4 driven zebrafish tumour models, and identify sensitivity of these tumours to BRD inhibition." (PMID 35504924, 2022). "In summary, this study demonstrated that IRF4 represents a novel regulator of PMN-MDSCs development in cancer, which may have predictive value for tumor progression." (PMID 33708218, 2021). "Moreover, the expressions of IRF4 and c-Myc in PMN-MDSCs and M-MDSCs from tumor patients was explored." (PMID 33708218, 2021). "However, we would like to note that the relationship between IRF4 and PMN-MDSCs in human tumors requires further detailed investigation in distinct tumor types before firm conclusions can be drawn." (PMID 33708218, 2021). "Importantly, the IRF4 expression level was negatively correlated with the PMN-MDSCs frequency and tumor development but positively correlated with c-Myc expression in clinical cancer patients." (PMID 33708218, 2021). "In detail, we found that all three tumor infiltrating B lymphocytes (TIL-B) subsets, activated or effector memory CD8+ and activated or effector memory CD4+T cells were significantly correlated with IRF4 expression (|r| > 0.3 and P < 0.001)." (PMID 34195096, 2021). "We, and others, have demonstrated that IRF4 genetic knockdown, or its targeting via the tumor suppressor miR-125b, is lethal for MM cells, irrespective of their genetics, making IRF4 a sort of “Achilles’ heel” for MM." (PMID 34769070, 2021). "However, it has also been shown that IRF4 overexpression in myeloid-derived suppressor cells induces a decreased suppressive effect on CD8+ T cell proliferation, resulting in less rapid tumor progression." (PMID 34898573, 2021). "IRF4 may have predictive value for determining the PMN-MDSCs level and tumor progression in cancer patients." (PMID 33708218, 2021). "Results showed that the expressions of IRF4 and c-Myc were down-regulated in PMN-MDSCs from tumor patients compared with those in the controls (P<0.05), but no significant change was detected in expression of IRF4 in M-MDSCs." (PMID 33708218, 2021). "A lower expression of IRF4 was found in CD11b+Gr1+cells (MDSC) compared with CD11b+Gr1- cells (no-MDSC) in the spleen of tumor-bearing mice." (PMID 33708218, 2021). "While in tumor cells, the staining level isn’t detected, the intensity is negative, and the quantity is none, which reveals that IRF4 expression is down-regulated in tumor tissues." (PMID 34020619, 2021). "Tumor cells produce high levels of actinic acid promoted by IL-13 to inhibit IRF4, skewing monocytes differentiation toward TAMs rather than DCs in multiple murine sarcoma models." (PMID 34625124, 2021). "Finally, 19 prognostic genes were verified by GSE17536 and GSE17537 from GEO, and five genes (ADAM23, ARHGAP20, ICOS, IRF4,MMRN1) were significantly different in tumour tissues compared with normal tissues at the protein level." (PMID 33949771, 2021).
tumor (continued). "Given the result that IRF4 is not expressed in polymorphonuclear cells, it was not surprising that the deletion of IRF4 in Ly6G+ cells in vivo did not influence tumor growth, overall survival or MDSC cell frequency." (PMID 32448983, 2020). "In line with the previous report, myeloid-specific deletion of IRF4 using the LysMCreIrf4fl/fl mice, accelerated tumor growth, but had no influence on the overall survival." (PMID 32448983, 2020). "Considering that a role for IRF4 in BC has never been explored, we next sought to investigate its potential tumor suppressor activity in this context." (PMID 32855526, 2020). "PMN cell (Ly6G)-specific depletion of IRF4, however, did not influence tumor progression or MDSC accumulation in vivo in accordance with our finding that IRF4 is not expressed in PMN-MDSC." (PMID 32448983, 2020). "IRF4 was expressed homogenously in monocytic cells in blood, spleen as well as tumor, and was independent of the tumor status." (PMID 32448983, 2020). "Any attempt to potentialize IMids effects or to downregulate IRF4 targeting other pathways failed to decrease its expression in WM tumor cells." (PMID 29348877, 2017). "We ruled out the role of various IRF4 regulatory mechanisms, and other pathways activating WM tumor cells, such as B cell activators." (PMID 29348877, 2017). "Importantly, the expression of JMJD3, IRF4 and BCL2 in tumor tissues derived from JMJD3 siRNA-treated mice were dramatically decreased when compared to tumors from the control animals." (PMID 27102442, 2016). "Decreased tumor burden, involving simultaneous MYC and IRF4 downregulation and apoptosis induction." (PMID 25849938, 2015). "With the caveat that gene expression assessments from primary tumour samples derive from mixed cell types, this confirmed that OCI-LY3 and LY10 fell within the general distribution of expression values for BATF and IRF4, and at the high end of the SPIB distribution." (PMID 24875472, 2014). "IRF-5, likely a tumor suppressor, is highly expressed in EBV transformed cells and, together with IRF-4, may be involved in the EBV-mediated regulation of Toll-like receptor 7 activities." (PMID 20209099, 2010). "Following coculture with E0771-Her2 tumor cells, A1R CAR T cells exhibited significantly increased production of IFNγ and TNF and increased expression of effector related genes PD-1 (Pdcd1), TIM-3 (Havcr2), Gzmb and Irf4 compared to control and A3R CAR T cells." (PMID 40610421, 2025). "The interaction between BATF and interferon regulatory factor 4 (IRF4) can reduce the expression of TOX, promote the effector differentiation of the transcriptional and epigenetic landscape of exhausted T cells, thereby improving the anti-tumor response of engineered T cells." (PMID 39342365, 2024). "Furthermore, cooperation of IRF4 and BATF could counteract T cell exhaustion and improve anti-tumor response of CAR-T cells." (PMID 38918817, 2024). "Given the multiple effects of IRF4 on immune cells, especially T cells, manipulating IRF4 may be an important therapeutic target for reversing T cell exhaustion and TME disorders, thus promoting anti-tumor immunity." (PMID 36814912, 2023). "Discrepancies in IRF4 prognostic values might be the result of differences in cutoff values that the authors defined to consider tumor cells positive or negative for IRF4." (PMID 36611989, 2023). "More importantly, the relationship between IRF4 and immunity was evaluated from several significant aspects including TIICs (tumor-infiltrating immune cells), a pair of classic immune checkpoint genes comprising of a receptor and its ligand (PD1 and PDL1), as well as the tumor microenvironment." (PMID 35664436, 2022). "Furthermore, it has been suggested that increased IRF4 expression in immune cells increases the ability of regulatory T cells to suppress TH2 responses, which may accelerate tumor growth." (PMID 34898573, 2021). "In contrast, IRF4 expression in polymorphonuclear cells in blood, spleen and tumor was absent." (PMID 32448983, 2020).
tumor (continued). "However, polymorphonuclear cells do not express IRF4 in tumor bearing mice and in line with that, the deletion of IRF4 in Ly6G+ cells did not alter tumor development." (PMID 32448983, 2020). "However, BTK inhibition using ibrutinib had no impact on IRF4 level in WM, nor did it increase WM tumor cells sensitivity to lenalidomide and pomalidomide." (PMID 29348877, 2017). "This inverse relationship suggests that while IRF4 promotes early B cell presence and TLS initiation, its sustained expression may hinder functional maturation, preventing the formation of germinal center-like structures essential for effective anti-tumor immunity." (PMID 40607252, 2025). "In addition to the increased levels of a macrophage marker in large tumors, our study suggests an association between the mRNA levels of the cytokines CCL5, CCL18, and GDF15, as well as the transcription factor IRF4, and VS tumor volume, which has not yet been investigated in VSs." (PMID 39272860, 2024). "No obvious differences in the distribution of age, sex, tumor location, staging, or IPI score were observed between the IRF4+ cases and those lacking IRF4 rearrangement (IRF4−)." (PMID 37081786, 2023). "Tumor purity is an important factor affecting the immune infiltration analysis of clinical tumor samples by genomic methods, TIMER database also indicated that IRF4 expression levels had a significant negative correlation with tumor purity." (PMID 36797470, 2023). "In our hands, specific deletion of IRF4 in PMN-MDSC has no influence on PMN-MDSC expansion, their T cell suppressive capacity, tumor growth or survival." (PMID 32448983, 2020). "Accordingly, IRF4 deletion in Ly6G+ cells had no influence on MDSC frequency, the suppressive function, tumor growth or survival." (PMID 32448983, 2020). "Because the tumor Ag is absent from the infected lung, the TCR is not ligated, and, hence, all routes leading to the activation of Blimp-1 and IRF4 are disabled." (PMID 30745900, 2019). "For example, IRF4 exhibited promoter hypomethylation in KIRP and THCA, no significant changes in promoter methylation in GBM, PCPG, SARC and SKCM, and high methylation levels in several tumours including BLCA, BRCA, CESC and COAD." (PMID 38130025, 2024). "The eight probes extracted from the RFECV method showing discriminative power between tumour and nontumour samples included cg17105014 (GYPC), cg23273897 (MME), cg22083047 (PRICKLE2), cg09396217 (ANGPT1), cg01049530 (BMP3), cg18237405 (CPNE5), cg12741420 (IRF4) and cg11754206 (KCNB2)." (PMID 36779430, 2023). "In contrast, in the case of Ag-experienced anti-tumor CD8+ T cells, due to the much smaller levels of tumor antigens presented with MHCs in the TME, the strength of the TCR signal in anti-tumor CD8+ T cells may not be enough to activate Blimp-1 and IRF4 species to suppress PD-1 expression." (PMID 30745900, 2019).